CXCL8 (C-X-C motif chemokine ligand 8)
Diseases named in the same sentence as CXCL8 in open-access papers (continued):
Sharing a sentence is not in itself a finding about the gene and the disease.
influenza (95 papers, 2011 to 2026). An acute viral infection of the respiratory tract, occurring in isolated cases, in epidemics, or in pandemics; it is caused by serologically different strains of viruses (influenzaviruses) designated A, B, and C, has a 3-day incubation period, and usually lasts for 3 to 10 days. "Elevated levels of IL-6 and CXCL8 consistently predict hospitalization and mortality in influenza patients." (PMID 41583233, 2025). "For example, during influenza infection, virally infected cells secrete Cxcl8 and granulocyte macrophage-colony stimulating factor to attract neutrophils." (PMID 39872517, 2024). "In an RCT of patients with influenza, combination therapy with oseltamivir and azithromycin showed significant improvement in the levels of inflammatory cytokines, such as IL-6, CXCL8/IL-8, IL-17, CXCL9/MIG, sTNFR-1, and IL-18." (PMID 37243228, 2023). "We report that both CXCL8 and CXCL10 modulate the pathways associated with influenza infection, such as the Toll-like receptor signalling pathway, Influenza A, and the RIG-I-like receptor signalling pathway." (PMID 37515084, 2023). "Additionally, influenza infection stimulated CXCL8 secretion by primary human alveolar epithelial cells." (PMID 39000173, 2024). "Role of Hypercytokinemia/hyperchemokinemia in the Pathogenesis of Influenza pathway was found to be significantly upregulated in the severe group’s monocytes with DEGs of AREG, CCL3, CCL4, CXCL8, IL1B, and ISG15 (coverage = 7% and p < 0.001)." (PMID 37495649, 2023). "During influenza, cytokines and chemokines such as type I and III interferons (IFNs), IL-6, CXCL8, CCL2, CCL3, CCL4, and CCL5 are produced at the site of infection (Wareing and others 2004)." (PMID 35674675, 2022). "PBMCs in seasonal influenza patients were activated and expressed cytokines ex vivo (e.g. IL-6, CXCL8/IL-8, CCL2/MCP-1, CXCL10/IP-10, CXCL9/MIG); their ‘responsiveness’ to stimuli was shown to change dynamically during the illness course." (PMID 22022504, 2011). "Third, the underlying mechanisms of MCEMP1 and SPARC genes contributing to the development of protective immunity after influenza vaccination should have been rigorously verified in multidimensions, especially the regulation of effector cytokines (CXCL 8/IL-8, Granzyme-B)." (PMID 33343577, 2020). "Whilst influenza infection increased the production of pro-inflammatory cytokines and chemokines, as with RSV infection, treatment with vitamin D either before or after influenza infection decreased gene expression of TNF-α, IFN-β, ISG15, CXCL8, IL-6 and RANTES (CCL5)." (PMID 26035247, 2015). "Adding further to this complexity, influenza and RSV infection can promote increased production of CXCL8/IL-8 upon subsequent re-stimulation with TLR3 ligands, suggesting that previous virus exposure can induce “trained” immunity that may be both beneficial and harmful to the host." (PMID 29552008, 2018).
schizophrenia (95 papers, 2011 to 2026). A major psychotic disorder characterized by abnormalities in the perception or expression of reality. "For instance, the haplotype of CXCL8 rs4073T/rs2227306C/rs1126647T is associated with an increased risk for schizophrenia." (PMID 38793070, 2024). "Increased levels of CXCL8 have also been associated with the clinical severity of schizophrenia measured by the PANSS scale." (PMID 35782435, 2022). "The patients with schizophrenia demonstrated higher levels of CXCL8 (p = 0.001) and lower levels of fractalkine (p = 0.041)." (PMID 35782435, 2022). "Increased CXCL8 and reduced fractalkine serum concentrations were recorded in patients with schizophrenia." (PMID 35782435, 2022). "Following on from these findings regarding the role of immune processes in schizophrenia development the present study evaluates the serum levels of anti-inflammatory cytokine IL-10, and pro-inflammatory chemokines CXCL8 and CX3CL1 in schizophrenic patients." (PMID 35782435, 2022). "Likewise, elevated levels of maternal CXCL8 has been implicated in increased risk of psychosis in offspring, likely due to disruption of early neurodevelopment, in keeping with the suggestion that schizophrenia may be a disorder of neurodevelopmental origin." (PMID 26441528, 2015). "Interestingly, CXCL8 gene shows differential expression in second-generation antipsychotic drug induced metabolic syndrome and impaired immune functions in schizophrenia patients." (PMID 41446805, 2025). "Moreover, increased neurotoxicity caused by increased levels of toxic cytokines (e.g., IL-1β, IL-6, IL-8, TNF-α, and IFN-γ) and chemokines (e.g., CCL11, CCL2, CXCL8, and CXCL10) is significantly associated with the G-CoDe and the schizophrenia phenome." (PMID 36256663, 2022). "The schizophrenia patients demonstrated significantly higher levels of serum CXCL8 (schizophrenia: 13.4 ± 15.7 pg/mL, control: 6.9 ± 4.2 pg/mL, p = 0.001) and lower level of serum fractalkine (schizophrenia: 22.8 ± 9.9 pg/mL, control: 45.4 ± 84.5 pg/mL, p = 0.041)." (PMID 35782435, 2022). "Although its precise role in the Central Nervous System remains unclear, current research suggest that serum CXCL8 levels are significantly increased in schizophrenia patients in comparison to healthy controls." (PMID 35782435, 2022). "Similarly, elevated levels of CXCL8 (IL8), and TNFα as well as the acute phase protein C-reactive protein (CRP) in maternal serum are linked to an increased risk of schizophrenia in offspring." (PMID 34858132, 2021). "Robust data, supported by meta-analyses, indicate elevated levels of CXCL8/IL-8, CCL2/MCP-1, CCL4/MIP-1β, and CCL11/eotaxin-1 in the bloodstream of individuals with schizophrenia." (PMID 41303622, 2025). "Meta-analyses data showed an increase in CXCL8/IL-8, CCL2/MCP-1, CCL4/MIP-1β, and CCL11/eotaxin-1 in the blood of patients with schizophrenia." (PMID 39457671, 2024). "The present study compares the levels of interleukin (IL)-10, interleukin-8 (CXCL8), and fractalkine (CX3CL1) between schizophrenia patients and healthy controls." (PMID 35782435, 2022). "Furthermore, heightened neurotoxicity resulting from elevated concentrations of toxic cytokines (e.g., IL-1β, IL-6, IL-8, TNF-αand IFN-γ) and chemokines (e.g., CCL11, CCL2, CXCL8 and CXCL10) is markedly correlated with the schizophrenia phenome." (PMID 41200225, 2025). "Besides, the most reliable data confirmed by the results of meta-analyses showed an increase in CXCL8/IL-8, CCL2/MCP-1, CCL4/MIP-1β, CCL11/eotaxin-1 in the blood of patients with schizophrenia." (PMID 36768537, 2023). "However, induced secretion of CXCL8 (but not IL-10), i.e., the ratio of PHA-stimulated to non-stimulated secretion, increased significantly in the schizophrenia group." (PMID 35782435, 2022).
Arthritis (93 papers, 2006 to 2026). Inflammation of a joint. "Elevated levels of CXCL8 are seen in synovial fluid and serum of patients with arthritis or gout, associated with increased neutrophil infiltration and hyperactivation in the joints." (PMID 36725964, 2023). "A dominant-negative mutated CXCL8 chemokine PA401 displaced wild-type chemokines from GAGs and had anti-inflammatory effects in murine lung inflammation, arthritis, acute renal damage, transplantation, and other animal models of neutrophil-driven inflammation." (PMID 36725964, 2023). "Our method was validated in patient samples and we confirmed the existence of natural NH2-terminally cleaved CXCL8 proteoforms in synovial fluids from arthritis patients." (PMID 33777041, 2021). "IL-1 and TNF-α stimulation of cells induce high CXCL8 levels in synovial tissue and fluid of inflamed joints, and anti-CXCL8 treatment prevents neutrophil infiltration and tissue damage in LPS/IL-1-induced arthritis in mice." (PMID 26284069, 2015). "Having applied these evaluation criteria, the CXCL8(Δ6F17KF21KE70KN71K) decoy protein was identified as the most promising CXCL8 mutant that was therefore further investigated in an acute (mBSA (methylated BSA)-induced) murine arthritis model." (PMID 23919527, 2013). "IL-8/CXCL8, a potent 8.5-kDa chemoattractant for neutrophils, plays a pivotal role in the recruitment and activation of neutrophils and is considered to be the most important inflammatory chemokine associated with arthritis." (PMID 24517278, 2013). "Therefore, CXCL8 might play a critical role in the early synovitis of arthritis that is characterized by vascular proliferation in the synovial membrane where CXCL8 can exert its effect." (PMID 38001449, 2023). "Overall, these results demonstrate that high levels of IL-6/sIL-6R, as those present in joints of patients with arthritis, may contribute to the amplification of the inflammatory response enhancing the production of IL-1β, CXCL8 and CCL2 by SFMCs and by RA synoviocytes." (PMID 25271853, 2014). "CXCL8-based decoy proteins prevented CXCR1 and CXCR2 signaling in neutrophils and ameliorated arthritis in AIA mice." (PMID 36860872, 2023). "CXCL1 and CXCL8 induce neutrophil chemotaxis in vitro, which is also inhibited by the blockade of CXCR1/CXCR2 and DF 2162, the later inhibiting neutrophil recruitment in zymosan-induced arthritis in mice and AIA in rats." (PMID 36860872, 2023).
oral cancer (93 papers, 2007 to 2026). "Higher CXCL8 levels were also observed in the serum of oral cancer patients with the T-allele or TT genotype, suggesting this may offer value as a biomarker suitable for use when detecting oral cancer." (PMID 38807156, 2024). "Given the upregulation of CXCL8 in most tumor tissues and the close association between cancer risk and two CXCL8 gene polymorphisms, the impact of different polymorphic loci on the production of CXCL8 was next assessed in oral cancer patients and healthy controls." (PMID 38807156, 2024). "Ultimately this approach revealed that serum CXCL8 concentrations were significantly higher in oral cancer patients harboring the TT + TC genotypes as compared to the CC genotype (P < 0.01)." (PMID 38807156, 2024). "Serum CXCL8 levels in oral cancer patients with the TT + TC genotypes were also significantly elevated as compared to levels in normal control subjects (P < 0.01)." (PMID 38807156, 2024). "Nevertheless, using ELISA, a recent study assessed the saliva of patients with oral cancer for the presence of both inflammatory chemokines (CXCL8, CXCL10, and CCL2), homeostatic chemokines (CXCL4, CCL14, and CCL18)." (PMID 24376459, 2013). "Furthermore, oral cancer patients carrying the CXCL8 +781 TT + TC genotypes exhibited pronounced increases in serum levels of CXCL8 as compared to the CC genotype (P < 0.01), and also shown similar trend as compared to genotype-matched normal controls (P < 0.01)." (PMID 38807156, 2024). "With the use of bioinformatics analysis of the gene expression profile of metastatic and non-metastatic lymph nodes and original tumors, we identified a novel oral cancer metastatic gene signature, FN1, CXCL8, and MMP9." (PMID 37640804, 2023). "For example, let-7c contributes to oral cancer stemness and radio/chemoresistance through suppressing CXCL8 (IL-8)." (PMID 33917482, 2021).
bladder cancer (91 papers, 1997 to 2025). "This revealed that TAM-derived CXCL8 is highly associated with bladder cancer migration, invasion, and angiogenesis." (PMID 32201645, 2020). "CXCL8 was also associated with amoebiasis and the bladder cancer pathway." (PMID 34174849, 2021). "Recently, CXCL8 was also proposed to be predominately overexpressed in tissues with bladder cancer, its overexpression was tightly associated with advanced disease, and the overall survival rate of patients with increased expression of CXCL8 was obviously reduced." (PMID 32766720, 2020). "For example, the infiltration of TAMs in the tumor microenvironment leads to the increase in CXCL8, which in turn promotes bladder cancer cells to secrete MMP-9, VEGF, and E-cadherin, enhancing the migration and angiogenic capacity of bladder cancer cells." (PMID 40131539, 2025). "Infiltrating TAMs can promote tumor development by altering the microenvironment of bladder cancer through the action of C-X-C motif chemokine ligand 8 (CXCL8)." (PMID 38542078, 2024). "Several chemokines within the CXCL family, such as CXCL1, CXCL2, CXCL5, CXCL8 (IL-8), and CXCL12, also play a crucial role in the recruitment of myeloid cells and TAM in bladder cancer, and are associated with tumor grading, staging, and metastasis." (PMID 39606239, 2024). "In bladder cancer, a high expression level of NCF2 was shown to be associated with an undesirable abundance of chemokine CXCL8, a marker of immunosuppressive MDSCs." (PMID 36672328, 2023). "In this study, we focused on CXCL8 secreted by TAM-like PBM-derived macrophages, and determined the critical role and biological effects of TAM-derived CXCL8 on bladder cancer cell production." (PMID 32201645, 2020). "The inhibition of CXCL8 with the CXCL8-neutralizing antibody reduced the ability of CXCL8 to promote VEGF secretion in bladder cancer cells, suggesting that CXCL8 in CM plays a role in this process." (PMID 32201645, 2020). "Since CXCL8 is mainly expressed in the cytoplasm of tumour cells, the expression levels were significantly higher in bladder cancer tissues than in normal tissues." (PMID 32201645, 2020). "Recently, one study revealed that TAM infiltration in the TME elevates CXCL8, promoting bladder cancer cell migration and invasion via the secretion of MMP9, VEGF, and E-cadherin." (PMID 32943996, 2020). "The infiltration of TAMs in the TME leads to the migration, invasion, and enhanced pro-angiogenic capacity of bladder cancer cells through CXCL8 secretion, which in turn regulates cadherin expression to accelerate cancer invasion." (PMID 32943996, 2020). "This study focused on the role of CXCL8 secreted by TAMs in promoting bladder cancer, but further work is needed to determine the full effect of microenvironment on tumors." (PMID 32201645, 2020). "The results show that CM increases bladder cancer cells’ invasion capacity, and this effect can be suppressed using an anti-CXCL8 neutralizing antibody." (PMID 32201645, 2020). "This was also demonstrated by ELISA at the protein level, indicating that CXCL8 can promote bladder cancer invasion by stimulating bladder cancer cells to secrete MMP-9." (PMID 32201645, 2020). "In summary, TAM-derived CXCL8 can promote the expression of MMP-9, VEGF, and E-cadherin in bladder cancer cells, causing changes in bladder cancer cell migration, invasion, and pro-angiogenic ability, and leading to the progression of bladder cancer." (PMID 32201645, 2020). "This demonstrates that CXCL8 derived from TAMs can increase bladder cancer cell migration by decreasing the expression of E-cadherin." (PMID 32201645, 2020). "We conducted a wound healing experiment to investigate the effect of CXCL8 on bladder cancer cell migration." (PMID 32201645, 2020). "Bladder cancer tissues spontaneously produce MDSCs-attracting CXCL8 (IL-8) and CCL22, which are correlated with poor prognosis of BCa." (PMID 29190997, 2017).
bladder cancer (continued). "Bladder cancer tissues spontaneously expressed high levels of the granulocyte/MDSC-attractant CXCL8 and Treg-attractant CCL22, but only marginal levels of the CTL-attracting chemokines: CCL5, CXCL9 and CXCL10." (PMID 25806105, 2015). "Therefore, targeting CXCL8 signaling presents a potential and promising therapeutic strategy for managing bladder cancer." (PMID 38542078, 2024). "We observed that BCG-induced inflammation in human bladder cancer tissues involves the induction of COX2 and its product PGE2, associated with the EP4-mediated induction of the chemokines CCL22 and CXCL8, which attract myeloid-derived suppressor cells (MDSCs) and regulatory T cells (Tregs)." (PMID 38667314, 2024). "CXCL8 produced by TAMs has the potential to induce the expression of VEGF in bladder cancer cells." (PMID 38542078, 2024). "Moreover, TAM levels show positive correlations with the expression of CXCL8 in bladder cancer tissues." (PMID 38542078, 2024). "To further investigate whether hub genes have an impact on the prognosis of bladder cancer, we performed survival analysis of CXCL8, MDM2, TGFB2, FN1, TIMP1, and RPL22L1, and their impact on tumor stage using TCGA database." (PMID 34276798, 2021). "By observing immunohistochemical section staining, we found that bladder cancer cells could also secrete CXCL8, meaning that there is complex intercellular communication in the tumor microenvironment involving autocrine and paracrine chemokines." (PMID 32201645, 2020). "The expression of CXCL8 in urine specimens and the tumour microenvironment of bladder cancer patients is significantly higher than that of healthy volunteers, and the overexpression of CXCL8 is positively correlated with significantly reduced survival of patients overall." (PMID 32201645, 2020). "Additionally, when the effect of CXCL8 was inhibited using an anti-CXCL8 neutralizing antibody, we observed that the ability of bladder cancer cells to promote angiogenesis, invasion, and metastasis was significantly reduced." (PMID 32201645, 2020). "The inhibition of CXCL8-signaling derived from TAMs may be a promising therapeutic approach in the treatment of bladder cancer." (PMID 32201645, 2020). "Moreover, CM derived from TAM-like PBM-derived CXCL8 could contribute to MMP-9 expression in bladder cancer cells, suggesting that it is also involved in bladder cancer invasion and metastasis." (PMID 32201645, 2020). "Since intratumoral expression of CXCL8 has been shown to be a negative prognostic marker, these observations highlight a potential for targeting the bladder cancer-associated chemokine microenvironments to improve the outcomes of BCG-treatment and chemotherapy of this cancer type." (PMID 25806105, 2015). "TAM-derived CXCL8 promotes MMP-9, VEGF, and E-cadherin expression in bladder cancer cells and enhances bladder cancer cell migration, invasion, and angiogenesis." (PMID 39199574, 2024). "To examine the potential consequences of recruiting macrophages into bladder cancer tumour microenvironments, we investigated the potential effect of TAM-derived CXCL8 on bladder cancer cell invasion." (PMID 32201645, 2020). "The infiltration of TAMs in the tumour microenvironment leads to the elevation of CXCL8, which in turn promotes the secretion of MMP-9, VEGF, and E-cadherin by bladder cancer cells." (PMID 32201645, 2020). "CXCL8 and MMP9 overexpression correlates with the poor prognosis of bladder cancer." (PMID 31681401, 2019). "Interestingly, untreated bladder cancer TMEs showed nearly a complete lack of effector cell-attracting chemokines but selective expression of Treg/MDSC attractants IL-8/CXCL8, CXCL-12, and CCL22." (PMID 38667314, 2024). "Immunohistochemistry (n = 55) was used to detect Chemokine (C-X-C motif) ligand 8 (CXCL8), CD163 (a TAM marker), Matrixmetalloproteinase-9 (MMP-9), vascular endothelial growth factor (VEGF), and E-cadherin in cancerous and adjacent tissues of bladder cancer patients." (PMID 32201645, 2020).
bladder cancer (continued). "In the present study, we observed that the high expression of CXCL8 in bladder cancer tissues positively correlated with the elevated expression of VEGF, suggesting that CM derived in vitro from TAM-like PBM can promote the secretion of VEGF from bladder cancer cells and blood vessel formation." (PMID 32201645, 2020). "This study found that the infiltration of TAMs in bladder cancer patients significantly increased when compared with the normal control, and TAM levels positively correlated with the expression of CXCL8 in bladder cancer tissues." (PMID 32201645, 2020). "Unexpectedly, we observed that, while BCG strongly up regulated the secretion of CXCL8 (P < 0.05) and CCL22 (P < 0.05) by ex vivo-treated bladder cancer explants (n = 11 patients), it did not enhance CXCL10 secretion." (PMID 25806105, 2015).